LCN1P1 (lipocalin 1 pseudogene 1)
Description:
May bind a variety of ligands including lipids.
Synonyms: LCN1L1; bA430N14.2
Gene: Unprocessed pseudogene on chromosome 9 (133,224,921 to 133,228,591, reverse strand). Ensembl gene ENSG00000119440.
Subcellular location: Secreted
Diseases named in the same sentence as LCN1P1 in open-access papers:
LCN1P1 is named in the same sentence as 4 diseases in open-access papers, as found by Europe PMC text mining. Sharing a sentence is not in itself a finding about the gene and the disease. The quoted sentences say what the papers report.
breast carcinoma (1 paper, 2025). "Of note, LCN1P1 and SV2C are also expressed in melanoma and other cancers such as breast cancers, respectively." (PMID 41026527, 2025).
thyroiditis (1 paper, 2025). Inflammation of the thyroid gland. "In addition, recombinant antibody p134 6w κ15, which recognizes lipocaline 1-like protein 1 (LCN1P1), that is highly expressed in the thyroid, was cloned from patient p134, who developed thyroiditis." (PMID 41026527, 2025).
LCN1P1 also shares sentences with these, for which no sentence is quoted: cancer (1 paper); melanoma (1).